DAB2IP (DAB2 interacting protein)
Diseases named in the same sentence as DAB2IP in open-access papers (continued):
Sharing a sentence is not in itself a finding about the gene and the disease.
epithelioid melanoma (1 paper, 2025). "This suggests that loss of DAB2IP is linked to dedifferentiated tumor types, whereas epithelioid melanoma maintains baseline expression despite its aggressive phenotype." (PMID 41374987, 2025). "In epithelioid melanoma, DAB2IP expression was largely comparable to that of the control." (PMID 41374987, 2025). "Taken together, DAB2IP was significantly reduced in RB, spindle, and myxoid melanoma, but not in epithelioid melanoma, suggesting that DAB2IP loss is more pronounced in more dedifferentiated histotypes." (PMID 41374987, 2025). "This pattern aligns with DAB2IP’s tumor-suppressor role, where its repression (epigenetic/microRNA) unleashes ERK/AKT/NF-κB signaling, proliferation, EMT, and resistance to apoptosis, while preserved expression in epithelioid melanoma suggests a reliance on alternative oncogenic programs." (PMID 41374987, 2025).
Ewing sarcoma (1 paper, 2024). A small round cell tumor that lacks morphologic, immunohistochemical, and electron microscopic evidence of neuroectodermal differentiation. "The NTRK gene and fusion partner was TPM3::NTRK1 (fibrosarcoma), LPPR1::NTRK2 (Ewing’s sarcoma), DAB2IP::NTRK2 (primitive neuroectodermal tumor), and RAD51B::NTRK3 (PTC)." (PMID 38967220, 2024). "Among pediatrics there was one case each of fibrosarcoma (TPM3::NTRK1), Ewing’s sarcoma (LPPR1::NTRK2), primitive neuroectodermal tumor (DAB2IP::NTRK2), and papillary thyroid carcinoma (RAD51B::NTRK3)." (PMID 38967220, 2024).
fibrosarcoma (1 paper, 2024). A malignant mesenchymal fibroblastic neoplasm affecting the soft tissue and bone. "Of the NTRK fusion partners we identified in pediatrics, TPM3::NTRK1 (fibrosarcoma) has been documented in pediatrics by others, and DAB2IP::NTRK2 (primitive neuroectodermal tumor) has been previously documented in adults." (PMID 38967220, 2024).
hypospadias (1 paper, 2022). Hypospadias is the displacement of the urethral meatus on the ventrum of the penis. "In the cohort of sporadic patients, we identified two additional variants in p38 MAPK signaling-related genes (TRIM67 and DAB2IP) potentially associated with hypospadias." (PMID 35606856, 2022).
metastatic tumors (1 paper, 2015). "The expression of DAB2IP was obviously decreased in hepatic, intestinal or pulmonary metastatic tumors in mice injected with DAB2IP KD cells." (PMID 26336990, 2015).
myeloid leukemia (1 paper, 2016). A clonal proliferation of myeloid cells and their precursors in the bone marrow, peripheral blood, and spleen. "Moreover, another study shows that gene fusion of DAB2IP may be another mechanism for disrupting DAB2IP function in myeloid leukemia." (PMID 26658103, 2016).
nasopharyngeal carcinoma (1 paper, 2024). A carcinoma arising from the nasopharyngeal epithelium. "Similarly, DAB2IP overexpression impaired proliferation, migration, and invasion of nasopharyngeal carcinoma (NPC) and osteosarcoma cells in vitro, and prevented lung metastasis of NPC injected in nude mice." (PMID 38902547, 2024).
neuroblastoma (1 paper, 2013). Neuroblastoma (NB) is the most common solid, extracranial childhood tumor. "In addition, the mRNA of DAB2IP expression did not significantly change on both hMSCs-differentiated osteogenic lineages or neuroblastoma SY5Y neuron differentiation system, therefore, the specificity for the role DAB2IP preferentially to the neuronal lineage from hMSCs." (PMID 24073285, 2013).
Obesity (1 paper, 2011). Accumulation of substantial excess body fat. "We supposed androgens may act as an intermediary for the close correlation between androgens and obesity and androgens, function on the expression of DAB2IP by suppressing EZH2 expression." (PMID 22046421, 2011).
ocular tumor (1 paper, 2025). "Integration with public datasets highlights CAV1 and GIPC1 as adverse survival correlates in UM and positions LRP2/CUBN/DAB2IP dysregulation as features of ocular tumor biology, nominating candidate biomarkers and mechanistic targets." (PMID 41374987, 2025). "Collectively, Megalin–Cubilin endocytosis, CAV1-mediated membrane signaling, and adaptor/tumor-suppressor nodes (GIPC1, DAB2IP) define axes that may govern differentiation, metabolic supply, and invasion in ocular tumors." (PMID 41374987, 2025).
prostate tumor (1 paper, 2013). "In this model, we implanted a human prostate tumor cell line which is deficient in a tumor suppressor protein DAB2IP (PC3-KD)." (PMID 23525451, 2013).
renal carcinoma (1 paper, 2020). A carcinoma arising from the epithelium of the renal parenchyma or the renal pelvis. "In recent years, with the deepening of epigenetic research, the epigenetic regulatory mechanisms of renal cancer, especially DNA methylation, are often used to predict the survival time of renal cancer, including DAB2IP, RCVRN, CRHBP, AR, and CDO1." (PMID 32733620, 2020).
retinoblastoma (1 paper, 2025). A malignant tumor that originates in the nuclear layer of the retina. "However, in retinoblastoma (GSE208143), LRP2 was downregulated, while CUBN, CAV1, GIPC1, and DAB2IP were upregulated." (PMID 41374987, 2025).
Type 2 diabetes (1 paper, 2024). "DAB2IP expression negatively correlated with Type 2 diabetes in the adipose tissue of obese patients, and in vitro studies showed reduced glucose uptake in DAB2IP-depleted adipocytes." (PMID 38902547, 2024).
urticaria (1 paper, 2025). A vascular reaction of the skin characterized by erythema and wheal formation due to localized increase of vascular permeability. "The DAB2IP (disabled homolog 2 interacting protein) gene mutation has been described in a family with HAE and urticaria." (PMID 41405015, 2025).
uveal melanoma (1 paper, 2025). A melanoma derived from melanocytes of the uveal tract. "Incorporating LRP2, CUBN, Caveolin-1, GIPC1, and DAB2IP into biomarker-driven clinical trial design could enhance risk stratification in uveal melanoma and RB and support the development of prognostic signatures that distinguish aggressive from indolent disease." (PMID 41374987, 2025). "Taken together, these analyses position GIPC1 as an independent prognostic biomarker and potential oncogenic driver in uveal melanoma, while DAB2IP functions as a protective tumor suppressor." (PMID 41374987, 2025). "To evaluate the prognostic relevance of LRP2, CUBN, DAB2IP, GIPC1, and CAV1 in uveal melanoma, we performed overall survival analysis using the GEPIA2 online platform." (PMID 41374987, 2025).
vitiligo (1 paper, 2024). Generalized well circumscribed patches of leukoderma that are generally distributed over symmetric body locations and is due to autoimmune destruction of melanocytes. "Regarding ECA25, six significant genomic regions were identified, although genes related to biological processes associated with vitiligo (TXN, LPAR1, SLC46A2, PRPF4, TRIM32, STOM, BRINP1, and DAB2IP) were only found in five of them." (PMID 39199954, 2024).
tumor (112 papers, 2005 to 2026). "As a promising biomarker, DAB2IP deficiency can promote chemoresistance and tumor recurrence in NMIBC after bladder-preserving surgery." (PMID 40361412, 2025). "We did not perform in vitro or in vivo manipulations (overexpression, knockdown, or knockout) of LRP2, CUBN, CAV1, GIPC1, or DAB2IP to establish causality between expression changes and tumor phenotypes." (PMID 41374987, 2025). "Accordingly, the loss of DAB2IP in tumor cells fosters metastasis and enhances chemo- and radioresistance." (PMID 40867592, 2025). "Future studies exploring the functional association between ER and NF-κB signaling in low DAB2IP ER+ tumors are needed to provide insight into mechanisms whereby this tumor subset exhibits aggressive oncogenic phenotypes." (PMID 39418101, 2024). "Saha and colleagues found that DAB2IP plays a role in the spindle assembly checkpoint (SAC) by contributing to the activation of PLK1 during mitosis; accordingly, DAB2IP loss impairs checkpoint functions, promoting tumor aneuploidy and related aggressiveness." (PMID 38902547, 2024). "Although its relevance in tumor initiation remains undefined, available evidences strongly indicate that loss of DAB2IP represents an advantage for cancer progression and metastasis." (PMID 38902547, 2024). "Consistent with this, genes upregulated in DAB2IP-low Luminal A tumors were shared with more aggressive tumor subtypes and were associated with proliferation, metastasis, and altered ER signaling." (PMID 39418101, 2024). "Loss expression of DAB2IP was observed to correlate closely with tumor aggressiveness and/or poor patient prognosis." (PMID 35248066, 2022). "Loss of DAB2IP induces malignant phenotypes of cancer cells, such as epithelial-mesenchymal transformation, tumor metastasis, and stemness through multiple signaling pathways." (PMID 35590292, 2022). "High EZH2 and low DAB2IP expression was associated with poor outcomes, including pathologic stage, tumor size, metastatic status and Fuhrman grade." (PMID 35562342, 2022). "With DOC treatment, DAB2IP inhibition associated with faster growth rate and bigger volume of tumour while DAB2IP overexpression associated with slower growth rate and smaller tumour volume." (PMID 36536485, 2022). "DAB2IP acts as a negative regulator of vascular endothelial growth factor signaling and angiogenesis, a tumor suppressor and was found to be associated with AD by a hippocampal TWAS study." (PMID 36684006, 2022). "In our study, we observed significantly decreased DAB2IP expression in tumour spheroids and docetaxel‐resistant cells, indicating that low DAB2IP expression was associated with chemoresistance in TNBC." (PMID 36536485, 2022). "Consistent with its earlier recognition as a ras/GAP tumor suppressor, DAB2IP also is associated with risk for various cancers and cancer cell proliferation and migration." (PMID 34140969, 2021). "DAB2IP expression was significantly associated with tumour size (P = 0.021) and TNM stage (P = 0.011)." (PMID 31713929, 2020). "Our results indicated that low DAB2IP expression was significantly associated with tumour size, TNM stage and a shorter overall survival time." (PMID 31713929, 2020). "DAB2IP, a novel tumor suppressor, is often downregulated in advanced stages of many types of cancer, and the loss of DAB2IP expression has been shown to correlate with the poor prognosis and increased tumor metastasis of many malignancies." (PMID 32943609, 2020). "We are convinced that loss of function of RasGAPs in cells that infiltrate the tumor environment, such as endothelial cells and fibroblasts, can have a dramatic impact on tumor development, as hinted by studies on DAB2IP and RASAL3." (PMID 33096593, 2020). "Our pilot study, which analyzed 46 men's diagnostic prostate biopsies for DAB2IP expression and had short follow up, showed that decreased DAB2IP tumor expression correlated with worse clinical outcome in the high‐risk population." (PMID 26471467, 2015).
tumor (continued). "Our prior pilot study analyzed 46 men's diagnostic prostate biopsies with high‐risk disease for DAB2IP expression and showed a strong correlation between pretreatment tumor DAB2IP reduction and worse clinical outcome with only 2.7 years of median follow up." (PMID 26471467, 2015). "Loss of DAB2IP expression is frequently detected in PCa cells and is associated with an increased risk for tumor metastasis." (PMID 25015118, 2014). "In general, loss of DAB2IP expression rvia epigenetic silencing during tumorigenesis is associated with the poor prognosis and tumor metastasis." (PMID 24073285, 2013). "Downregulation of DAB2IP in RCC has been associated with increased tumor growth and metastasis." (PMID 40361412, 2025). "Loss of DAB2IP expression has been linked to aggressive tumor behavior in BCa." (PMID 40361412, 2025). "Furthermore, cell cycle genes such as CDK5, CCNA2, CCNB1, and CCNB2, associated with tumor relapse and metastasis, are more highly expressed in DAB2IP-low Luminal A tumors." (PMID 39418101, 2024). "Together these evidences support the hypothesis that interfering with miRNA-mediated inhibition may restore the tumor-suppressive function of DAB2IP and revert aggressive phenotypes caused by the loss of its function both in tumor and in nearby stromal cells." (PMID 38902547, 2024). "In fact, a GAP-deficient mutant DAB2IP (R289L) was unable to suppress tumor growth, but significantly reduced metastasis, indicating that the RasGAP activity is required to inhibit tumor growth while other DAB2IP functions are involved in preventing tumor dissemination." (PMID 38902547, 2024). "In mouse xenografts, loss of either RASAL2 or DAB2IP alone was sufficient to promote tumor growth." (PMID 38902547, 2024). "Also, our data showed that DAB2IP inhibition significantly associated with decreased percentage of apoptotic cell and overexpression of DAB2IP associated with increased percentage of apoptotic cell in tumours with DOC treatment." (PMID 36536485, 2022). "DAB2IP acts as a tumour‐suppressor commonly loss in several cancers." (PMID 36536485, 2022). "Loss of DAB2IP could enhance tumor growth and resistance to mTOR-targeted therapies and ionizing radiation in RCC." (PMID 35562342, 2022). "Our present identification of an association between another tumor-suppressor gene, DAB2IP, and CAD survival outcomes in the present GWA screening underscores the importance of considering antagonistic pleiotropy when seeking to identify genetic effects in complex diseases." (PMID 34140969, 2021). "Decreased DAB2IP expression is found in PCa with increased risk of tumor metastasis." (PMID 28081154, 2017). "Here, we summarize the present understanding of the tumor suppressive role of DAB2IP in cancer progression; the mechanisms underlying the dysregulation of DAB2IP; the gene functional mechanism and the prospects of DAB2IP in the future cancer research." (PMID 26658103, 2016). "DAB2IP loss may be a genetic explanation for the observed differences in aggressive tumor characteristics and radiation resistance." (PMID 26471467, 2015). "Furthermore, loss of DAB2IP expression during tumorigenesis is associated with poor prognosis and increased tumor metastasis." (PMID 24912918, 2014). "Importantly, aberrant expression of ERα/β is associated with a variety of cancers, suggesting that ERβ-dependent regulation of DAB2IP might be implicated in other tumor types." (PMID 33096593, 2020). "All these data indicate that DAB2IP loss in PCa cells could maintain tumor growth after ADT." (PMID 26512963, 2015). "The DAB2IP gene, initially characterized as a tumor suppressor, serves as a multifunctional regulator and performs roles in both the cardiovascular and neurological systems." (PMID 41798622, 2026).
tumor (continued). "The tumour‐suppressor DAB2IP (Disabled homologue 2 interacting protein) is a RasGAP and negatively controls Ras‐dependent mitogenic signals." (PMID 40263693, 2025). "Because subtype-resolved ocular data for DAB2IP are limited, we interpret these findings alongside its established tumor-suppressor functions." (PMID 41374987, 2025). "This suggests that the suppression of genome instability via the PLK1-mediated signaling pathway is likely a crucial aspect of DAB2IP’s ability to inhibit tumor development." (PMID 41261855, 2025). "DAB2IP is often lost in the early stages of tumor development, resulting in the production of inflammatory mediators and an enrichment of macrophages, suggesting a potential role for DAB2IP in remodeling the tumor immune microenvironment." (PMID 41261855, 2025). "In one study, high DAB2IP mRNA expression correlated with smaller tumor volume and better survival outcomes compared to patients with low expression." (PMID 40361412, 2025). "Various studies demonstrated that restoring DAB2IP expression in DAB2IP-depleted cancer cells reverses metastatic behavior and drug resistance both in vitro and in vivo, in multiple tumor types." (PMID 40867592, 2025). "DAB2IP, a Ras GTPase‐activating protein, functions as a tumour suppressor and is involved in various cellular processes, including cell growth, migration, and signal transduction." (PMID 40263693, 2025). "From a pharmacological perspective, our data support previous findings that suggest the repurposing of thiostrepton for cancer treatment, revealing DAB2IP as a possible contributor to its tumor-suppressive activity." (PMID 40867592, 2025). "Although these cancers share common RASGAP pathway components, such as DAB2IP, the extent of pathway involvement and its functional significance can differ due to variations in molecular context, tumor biology, and genetic alterations." (PMID 40361412, 2025). "The tumor suppressor DAB2IP is frequently downregulated in various human malignancies by multiple mechanisms, but is rarely deleted or mutated." (PMID 40867592, 2025). "Given the tumor suppressive activity of DAB2IP, we also considered as potential hits compounds that increased the Lum/Fluo ratio with an inhibitory effect on cell viability." (PMID 40867592, 2025). "We suggest that reactivation or upregulation of DAB2IP would concurrently attenuate multiple oncogenic pathways in both cancer cells and the tumor microenvironment, with implications for improved treatment of a broad spectrum of tumors." (PMID 38902547, 2024). "Recent studies showed that DAB2IP counteracts tumor growth and metastasis also cooperating with other tumor suppressors." (PMID 38902547, 2024). "This review summarizes recent insights into the tumor-suppressive functions of DAB2IP and the consequences of its inactivation in cancer." (PMID 38902547, 2024). "They found that loss of DAB2IP in ECs amplifies VEGFR2 signaling and the secretion of molecules involved in EMT and angiogenesis, and this increases tumor neovascularization and generates a pre-metastatic microenvironment." (PMID 38902547, 2024). "Observations made in the last decade revealed novel regulatory mechanisms involved in modulating DAB2IP action, and further confirmed its role as a tumor suppressor and promising therapeutic target." (PMID 38902547, 2024). "In line with its tumor-suppressive role, DAB2IP is frequently inactivated in cancer by transcriptional and post-transcriptional mechanisms, including promoter methylation, microRNA-mediated downregulation, and protein-protein interactions." (PMID 38902547, 2024).